CFAP44 (cilia and flagella associated protein 44)
Description:
Flagellar protein involved in sperm flagellum axoneme organization and function.
Synonyms: WDR52; FLJ11142; SPGF20
Tractability: Small molecule: a structure with a bound ligand is known. PROTAC: ubiquitination databases record sites on it.
Gene: Protein-coding gene on chromosome 3 (113,286,930 to 113,441,610, reverse strand). Ensembl gene ENSG00000206530.
Subcellular location: Cell projection, cilium, flagellum; Cytoplasm, cytoskeleton, flagellum axoneme
Gene Ontology:
Molecular function: peptidase activity; protein binding
Biological process: microtubule cytoskeleton organization; sperm axoneme assembly; flagellated sperm motility
Cellular component: axoneme; motile cilium
Genetic constraint (gnomAD): Loss-of-function variants: 115 observed, 192.7 expected, observed/expected ratio (o/e) 0.6, 90% interval 0.51 to 0.7. The upper end of that interval is the gene's LOEUF score, 0.7, which puts it in group 2 of 6, group 1 being the genes least tolerant of losing a copy. Missense variants: 1,913 observed, 2,143.7 expected, observed/expected ratio (o/e) 0.89, 90% interval 0.86 to 0.93. Synonymous variants: 673 observed, 721.81 expected, observed/expected ratio (o/e) 0.93, 90% interval 0.87 to 0.99.
Homologues: Orthologues: chimpanzee CFAP44 (99% identical), macaque CFAP44 (90% identical), pig CFAP44 (84% identical), dog CFAP44 (83% identical), rabbit CFAP44 (81% identical), rat Cfap44 (76% identical), mouse Cfap44 (76% identical), tropical clawed frog cfap44 (52% identical), Drosophila melanogaster CG34124 (25% identical). Paralogues in human: EML5 (13% identical), EML6 (12% identical), EML4 (10% identical), WDR90 (9% identical), EML1 (8% identical), CFAP251 (8% identical), EML3 (8% identical), EML2 (8% identical), CFAP52 (6% identical).
Diseases named in the same sentence as CFAP44 in open-access papers:
CFAP44 is named in the same sentence as 9 diseases in open-access papers, as found by Europe PMC text mining. Sharing a sentence is not in itself a finding about the gene and the disease. The quoted sentences say what the papers report.
male infertility (6 papers, 2018 to 2022). The inability of the male to effect fertilization of an ovum after a specified period of unprotected intercourse. "Recent whole-exome sequencing of men with MMAF (multiple morphological abnormalities of the flagella) revealed that biallelic mutations in CFAP43 and CFAP44 result in diverse morphological sperm defects and male infertility." (PMID 29687140, 2018). "Intriguingly, CFAP44, which is mutated in human male infertility and hydrocephaly, was recently found to be also an RNA-binding protein localizing to DynAPs, although whether it functions as an RBP in translational control of motile cilia assembly remains unclear." (PMID 34338635, 2021). "Motility mutants analysed in our screen also included deletions of genes with human orthologs linked to ciliopathies (such as hydin) or male infertility (CFAP43 and CFAP44)." (PMID 31242261, 2019). "All individuals with CFAP43 or CFAP44 mutations were unrelated; to our knowledge, none carried rare variants in genes previously reported to be associated with male infertility." (PMID 29449551, 2018).
infertile (3 papers, 2018 to 2022). "Furthermore, Cfap44−/− male mice also show flagellar immotility, leading to infertility." (PMID 35886074, 2022). "A recent study analyzed the expression of CFAP44 and CFAP44-AS1 (an antisense lncRNA of the CFAP44 gene) in infertile men with sperm motility and morphology defects and observed a significant reduction in the expression of CFAP44 and CFAP44-AS1." (PMID 35886074, 2022).
asthenozoospermia (1 paper, 2022). "It was found that both CFAP44 and CFAP44-AS1 were downregulated in patients with asthenozoospermia, and a positive correlation was also observed between CFAP44 and CFAP44-AS1 expression, as well as between both genes’ expression and sperm motility." (PMID 36290414, 2022).
osteosarcoma (1 paper, 2023). A usually aggressive malignant bone-forming mesenchymal neoplasm, predominantly affecting adolescents and young adults. "The results showed that 79 DEGs affected the prognosis of osteosarcoma, with PDE4C, CFAP44, CARNS1, GREB1L, ROF207 identified as significant risk factors and GBP1, MSC, GBP3, F13A1, CCL2 as substantial protective factors." (PMID 37796192, 2023).
CFAP44 also shares sentences with these, for which no sentence is quoted: cancer (1 paper); ciliopathies (1); dysplasia of fibrous (1); hydrocephaly (1); prostate (1).